KRT19 (keratin 19)
Description:
Involved in the organization of myofibers. Together with KRT8, helps to link the contractile apparatus to dystrophin at the costameres of striated muscle.
Synonyms: K19; CK19; K1CS; MGC15366
Tractability: Antibody: its Gene Ontology location is reachable by antibodies, with high confidence. PROTAC: ubiquitination databases record sites on it; its protein half-life has been measured.
Gene: Protein-coding gene on chromosome 17 (41,523,613 to 41,528,308, reverse strand). Ensembl gene ENSG00000171345.
Subcellular location (Human Protein Atlas): Intermediate filaments
Pathways (Reactome):
Developmental Biology: Developmental Lineage of Mammary Gland Alveolar Cells; Developmental Lineage of Mammary Gland Luminal Epithelial Cells; Developmental Lineage of Pancreatic Ductal Cells; Differentiation of Keratinocytes in Interfollicular Epidermis in Mammalian Skin; Formation of the cornified envelope; Keratinization
Gene Ontology:
Molecular function: protein binding; structural constituent of muscle; structural constituent of cytoskeleton; structural constituent of skin epidermis; protein-containing complex binding; structural molecule activity
Biological process: response to estrogen; sarcomere organization; epithelial cell differentiation; intermediate filament organization; morphogenesis of an epithelium
Cellular component: cell periphery; costamere; extracellular exosome; intermediate filament cytoskeleton; plasma membrane; cytoskeleton; cytosol; intermediate filament; keratin filament; apicolateral plasma membrane; dystrophin-associated glycoprotein complex; sarcolemma; terminal web; Z disc
Genetic constraint (gnomAD): Loss-of-function variants: 23 observed, 41.58 expected, observed/expected ratio (o/e) 0.55, 90% interval 0.4 to 0.78. The upper end of that interval is the gene's LOEUF score, 0.78, which puts it in group 3 of 6, group 1 being the genes least tolerant of losing a copy. Missense variants: 514 observed, 566.45 expected, observed/expected ratio (o/e) 0.91, 90% interval 0.84 to 0.98. Synonymous variants: 240 observed, 246.5 expected, observed/expected ratio (o/e) 0.97, 90% interval 0.88 to 1.08.
Homologues: Orthologues: chimpanzee KRT19 (99% identical), macaque KRT19 (98% identical), pig KRT19 (90% identical), guinea pig KRT19 (85% identical), mouse Krt19 (83% identical), rat Krt19 (82% identical), tropical clawed frog krt70 (53% identical), zebrafish krt93 (51% identical), zebrafish krt94 (51% identical), zebrafish krt95 (48% identical), zebrafish si:ch211-156l18.7 (45% identical). Paralogues in human: KRT14 (66% identical), KRT15 (65% identical), KRT16 (65% identical), KRT17 (64% identical), KRT13 (62% identical), KRT12 (58% identical), KRT10 (57% identical), KRT24 (53% identical), KRT9 (53% identical), KRT36 (52% identical), KRT27 (51% identical), KRT28 (50% identical), and 56 more.
Diseases named in the same sentence as KRT19 in open-access papers:
KRT19 is named in the same sentence as 333 diseases in open-access papers, as found by Europe PMC text mining. Sharing a sentence is not in itself a finding about the gene and the disease. The quoted sentences say what the papers report.
breast carcinoma (238 papers, 1996 to 2026). "Another gene downregulated within Subtype 1, KRT19, has been significantly linked to poor prognosis in breast cancer patients." (PMID 40004168, 2025). "Subsequently, KRT19 was identified as tumor-associated biomarker in various cancers, including esophageal squamous cell carcinoma, cervical cancer, breast cancer and HCC 26-29." (PMID 33442422, 2021). "Cytokeratin 19, which belongs to the intermediate filament, causes a reduction in cell motility and growth and affect drug resistance in breast cancer through the enhancement of p38 signalling." (PMID 31963677, 2020). "We revealed that high expression of KRT19 (median values as the cutoff) was significantly correlated with good outcomes in breast cancer, whereas a poor prognosis was associated with colon cancer patients with high KRT19 expression." (PMID 30650643, 2019). "From the sequencing results, we determined that RAC1 mRNA sequences were the same in both colon and breast cancer cells, whereas the KRT19 mRNA sequence showed a silent mutation, T→C (on 471 bp), in breast cancer cells alone." (PMID 30650643, 2019). "Our data also evidences that KRT19 expression is significantly associated with clinical outcomes in breast cancer." (PMID 29747452, 2018). "Among the 54 keratins, keratin 19 (KRT19) is the smallest one, and is of peculiar interest because of its implication as a diagnostic biomarker of circulating cells in breast cancer." (PMID 26460615, 2015). "An automated procedure consisting of two variant methods for quantifying the cytokeratin-19 (CK19) marker in breast cancer tissues is presented." (PMID 26329009, 2015). "Notably, aberrant KRT19 expression has been implicated in tumor proliferation, metastasis and survival in hepatocellular carcinoma, breast cancer, colorectal cancer, and is closely associated with the prognosis of various tumors." (PMID 41345704, 2025). "In humans, peripheral blood cytokeratin 19 (CK19) mRNA-positive circulating tumor cells (CTCs) was utilized to identify early-stage breast cancer patients with micrometastatic disease who are at risk for disease progression and monitor treatment response in patients with advanced disease." (PMID 35948591, 2022). "Also, increased levels of KRT19 mRNA in CTCs during metastasis are associated with worse patient survival, and K19 has been shown to be even released by breast cancer cells of high metastatic potential." (PMID 33393839, 2021). "Before comparing the detailed molecular mechanisms associated with KRT19 expression in colon and breast cancer cells, we hypothesized that whether KRT19 interacts with the β-catenin/RAC1 complex to regulate Wnt/Notch signaling crosstalk." (PMID 30650643, 2019). "For example, circKRT19 expression derived from KRT19, a notch signaling regulator in breast cancer, is significantly associated with higher ERBB3 expression in mRNA (Wilcoxon rank-sum test, FDR < 2.2 × 10− 16) and protein levels (Wilcoxon rank-sum test, FDR = 7.91 × 10− 11)." (PMID 31446897, 2019). "Sequences of KRT19 mRNA in colon and breast cancers show one silent mutation in breast cancer only, which might influence NUMB transcriptional activity." (PMID 30650643, 2019). "Loss or down regulation of KRT19 is associated with an aggressive behavior characterized by enhanced migratory, adhesive and invasive properties in squamous cell carcinomas, neuroblastomas, renal and breast cancers." (PMID 26460615, 2015). "In breast cancer, KRT19 is found to mediate cell cycle arrest, a typical characteristic of senescence by physically interacting with GSK3β and thus restrain GSK3β-dependent degradation of cyclin D3." (PMID 41345704, 2025). "Cytokeratin 19 is highly expressed in luminal A subtype breast cancer and affects the proliferation of cancer cells." (PMID 40699615, 2025). "It has been documented that KRT19 expression is downregulated when ERα is knocked down in breast cancer." (PMID 39453570, 2025).
breast carcinoma (continued). "Explore clinical and translational applications: Long-term studies will investigate CuNPs’ safety and efficacy in clinical settings through pilot clinical trials, stratifying patients by KRT19 expression and breast cancer subtype." (PMID 40806403, 2025). "This study investigates the effects of copper nanoparticles (CuNPs) on KRT19 gene expression in four breast cancer cell lines (MDA-MB-231, MDA-MB-468, MCF7, and T47D), representing triple-negative and luminal subtypes." (PMID 40806403, 2025). "Copper nanoparticles (CuNPs) significantly reduce KRT19 expression in breast cancer cell lines, with greater suppression in epithelial-like subtypes (e.g., MDA-MB-468, FC = 0.32 at IC50) compared with mesenchymal-like subtypes (e.g., MDA-MB-231, FC = 0.51)." (PMID 40806403, 2025). "OSNA (one-step nucleic acid amplification) is a method for determining the semi-quantitative amount of cytokeratin 19 mRNA for the intraoperative assessment of the occurrence of metastases in sentinel lymph nodes (SLNs) in breast cancer." (PMID 39859370, 2025). "This study investigates CuNPs’ effects on KRT19 expression across four breast cancer cell lines (MDA-MB-231, MDA-MB-468, MCF7, and T47D), representing TNBC and luminal subtypes." (PMID 40806403, 2025). "While CuNPs’ anticancer effects have been documented, their impact on KRT19 expression in breast cancer remains underexplored." (PMID 40806403, 2025). "The current study provides a robust foundation for understanding the subtype-specific effects of copper nanoparticles (CuNPs) on KRT19 expression in breast cancer cell lines, but its in vitro design presents several limitations." (PMID 40806403, 2025). "A low expression of KRT19 in breast cancer patients was attributed to higher tumor cell proliferation." (PMID 40004168, 2025). "In a previous study, FBLN2 has been poorly expressed in seven human breast cancer cell lines where KRT19 (luminal marker) was highly expressed." (PMID 39110274, 2024). "A study on breast cancer demonstrated that increased KRT19 expression was correlated with breast cancer invasiveness." (PMID 38639039, 2024). "We aimed to evaluate and summarize the value of the OSNA assay for the diagnosis of SLN metastasis in cytokeratin 19 (CK19)-positive breast cancer." (PMID 39314227, 2024). "On the other hand, a TG2–dependent covalent CXCL12–keratin-19 (KRT19) heterodimer was described in breast cancer cells." (PMID 39544364, 2024). "For instance, KRT18 induces an epithelial–mesenchymal transition (EMT) in human breast cancer and KRT19 plays a critical role in breast cancer proliferation." (PMID 36672349, 2023). "The tumor-specific marker genes (i.e. EPCAM, KRT8, EPCAM, B2M, FCA1 and KRT19) were also highly expressed in the tumor regions of prostate, colorectal, liver cancer, pancreas and breast cancer." (PMID 36243975, 2023). "We have previously shown that the detection of cytokeratin-19 (CK-19) transcripts in CTCs by RT-qPCR in breast cancer patients is of prognostic significance before, during and after adjuvant chemotherapy." (PMID 36690653, 2023). "In contrast, cells expressing lower levels of KRT19 displayed increased level of stem cell markers, colony-formation activity and drug resistance in breast cancer." (PMID 36610719, 2023). "To date, no study has been conducted to explore the mechanism of KRT19 and the correlation between the expression of KRT19 and immune infiltration in breast cancer (BRCA)." (PMID 36292723, 2022). "Lastly, as for the correlation between KRT19 and the clinicopathological characteristics within breast cancer patients, more clinical specimen data should be collected and verified." (PMID 36292723, 2022). "The KRT locus of keratin family, KRT19, is a tumor suppressor gene in breast cancer and regulates drug sensitivity through cancer stem cell reprogramming and NOTCH signaling pathways." (PMID 36142451, 2022).
breast carcinoma (continued). "Firstly, it was indicated that KRT19 was specifically highly expressed in breast cancer at the mRNA and protein levels." (PMID 36292723, 2022). "KRT19, as a serum tumor marker for breast cancer, is mainly localized in the cytoskeleton and cytosol in cells, which is currently more widely used in the early diagnosis of BRCA." (PMID 36292723, 2022). "To explore the correlation between KRT19 expression and clinicopathological characteristics of breast cancer patients, we divided breast cancer patients into a KRT19 high-expression group and a low-expression group according to KRT19 expression." (PMID 36292723, 2022). "Similar findings were reported in breast cancer and hepatocellular carcinoma; KRT19 expression correlated with poor prognosis in breast cancer and predicted early postoperative recurrence in hepatocellular carcinoma." (PMID 36033462, 2022). "Cancer cells in human pancreatic, colorectal, and breast cancers are coated with the chemokine CXCL12 in the form of covalent heterodimers with keratin-19." (PMID 35046049, 2022). "In this study, we found that KRT19 methylation levels were significantly downregulated in breast cancer patients." (PMID 36292723, 2022). "In turn, CPTAC data suggest the downregulation of MMP-9 in breast cancer patients and upregulation of KRT19 (CK19)." (PMID 34884588, 2021). "Analysis of the RNA-seq data showed that KRT19 (CK19) mRNA is overexpressed in the TCGA breast cancer cohort compared to normal tissue." (PMID 34884588, 2021). "As previously reported, the expression of KRT19 is especially high in breast cancer, and KRT19 mRNA has been a suitable marker for identifying micrometastasis of breast cancer to lymph nodes and used for circulating tumor cell detection." (PMID 34122526, 2021). "A cytoskeletal protein keratin 19 (K19) is highly expressed in breast cancer but its effects on breast cancer cell mechanics are unclear." (PMID 33393839, 2021). "In mammary cancer, KRT19 was reported to interact with β-catenin/RAC1 complex and then upregulate NUMB expression, thus suppressing Notch signaling." (PMID 33767587, 2021). "The two most up-regulated AR responsive genes FADS1 and KRT19 are likely to be targets of both AR and ERβ, where FADS1 has been shown to be regulated by estrogen, and KRT19 expression correlating to estrogen receptor expressing breast cancer." (PMID 32413024, 2020). "Here, we found that silencing of KRT19 led to decreased cell proliferation, migration, and sphere formation in colon cancer and that these phenomena contrasted with those found in breast cancer." (PMID 30650643, 2019). "KLK5 not only regulates KRT19 expression to increase the malignancy of ovarian cancer cells strongly, but also induces miRNA-mediated anti-oncogenic pathways in breast cancer." (PMID 31572680, 2019). "Cytokeratin 19 (CK19) represents the type I acidic cytokeratins that are expressed in many epithelial malignancies, such as lung cancer, breast cancer, cervical carcinoma, colorectal carcinoma and papillary thyroid carcinoma." (PMID 31767040, 2019). "Surprisingly, we found upregulated Notch signaling targeted gene expression in breast cancer cells, whereas this signaling was downregulated in colon cancer cells upon KRT19 suppression." (PMID 30650643, 2019). "In breast cancer, KRT19 knockdown led to an increase in cancer properties because of attenuated Wnt and enhanced Notch signaling." (PMID 30650643, 2019). "High levels of mRNA encoding mammaglobin, CK-19 (keratin 19) and HER2/neu (Erb-B2 receptor tyrosine kinase 2), which are specific markers of breast cancer, are also found in the blood plasma of patients with given disease." (PMID 31572192, 2019). "Although knockdown of KRT19 increased cancer properties in breast cancer cells, suppression of KRT19 expression showed the opposite effect in colon cancer cells." (PMID 30650643, 2019).
breast carcinoma (continued). "Previously, several studies have shown the differential roles of KRT19 in proliferation and invasiveness among different cancers such as breast cancer, hepatocellular carcinoma, and colon cancer." (PMID 30650643, 2019). "As we showed in our previous study, knockdown of KRT19 in breast cancer promoted cancer properties, which contrasts with the function of KRT19 in other cancers." (PMID 30650643, 2019). "In this context, it is interesting to note that KRT19 is a well-established epithelial CSC marker that is used clinically to identify metastatic breast cancer cells in sentinel lymph node biopsies." (PMID 31311889, 2019). "Currently, the molecular detection of keratin 19 (KRT19) is a routine method in the clinical practice of breast cancer." (PMID 31331335, 2019). "In this study, we identify KRT19 as a suppressor of breast cancer, which is consistent with results of our previous study showing that it is an enhancer of colon cancer growth." (PMID 30650643, 2019). "Previously, we reported that KRT19 binds to the β-catenin/RAC1 complex in breast cancer cells, and another research group found that RAC1 plays vital roles in β-catenin localization." (PMID 30650643, 2019). "As KRT19 plays a differential role in cancer progression, here, we aimed to compare the roles of KRT19 in colon and breast cancer cells." (PMID 30650643, 2019). "We found that KRT19 expression was increased in both colon and breast cancer, but that knockdown of KRT19 showed opposing effects on cancer properties." (PMID 30650643, 2019). "Through this study, we provide a new perspective on KRT19 in the Wnt/β-catenin/Notch signaling pathway and the differential governance of cancer properties in colon and breast cancers." (PMID 30650643, 2019). "Our previous study showed that breast cancer properties were intensely upregulated upon KRT19 knockdown through the upregulation of Notch signaling, which was mediated by the Wnt/β-catenin/NUMB axis." (PMID 30650643, 2019). "In detail, silencing of KRT19 expression led to decreased cell proliferation, migration, and sphere formation in colon cancer cells, although the opposite effect was observed in breast cancer cells upon KRT19 knockdown." (PMID 30650643, 2019). "The expression of β-catenin protein was also attenuated both in colon and breast cancers in KRT19 knockdown cells." (PMID 30650643, 2019). "In this study, we found that the transcription level of β-catenin was suppressed dramatically upon KRT19 knockdown in colon and breast cancer cells." (PMID 30650643, 2019). "KRT19 is currently used clinically to identify metastatic breast cancer cells in sentinel lymph-node biopsies." (PMID 31311889, 2019). "KRT19 is a well‐established epithelial CSC marker that is used clinically to identify metastatic breast cancer cells in sentinel lymph node biopsies." (PMID 31311889, 2019). "KRT19 expression, however, is also known to be negatively correlated with cancer progression in breast cancer stem cell-like cells and cell lines." (PMID 29747452, 2018). "Here, we investigated the function of KRT19 in cancer reprogramming and drug resistance in breast cancer cells." (PMID 29747452, 2018). "In this study, we found the downregulated KRT19 expression pattern in breast cancer tissue when compared to the adjacent normal tissue, which is an agreement with Oncomine database." (PMID 29747452, 2018). "Concurrently, we showed that KRT19 regulates breast cancer cell migration and EMT (epithelial to mesenchymal transition)-responsive gene expression." (PMID 29747452, 2018). "In our previous study, we revealed the role of KRT19 as signaling component which mediated Wnt/NOTCH crosstalk through NUMB transcription in breast cancer." (PMID 29747452, 2018). "In conclusion, our current study has revealed that there is an inverse relationship between the expression of KRT19 and breast cancer progression." (PMID 29747452, 2018).